SHBG (sex hormone binding globulin)
Diseases named in the same sentence as SHBG in open-access papers (continued):
Sharing a sentence is not in itself a finding about the gene and the disease.
hyperlipidemia (9 papers, 2021 to 2025). "Deficiency in thyroid hormones can also be associated with weight gain and excess body mass, hyperlipidemia, decreased sex hormone-binding globulin (SHBG) levels and increased conversion of androstenedione to testosterone." (PMID 36673125, 2023). "Some researchers found that the serum level of sex hormone binding globulin in the patients with hyperlipidemia decreased, and that free testosterone levels increased, which would reduce the sensitivity of ovary to Gn." (PMID 38033994, 2023). "It was believed that the pregnant women with GDM tend to have lower steroid hormones and sex hormone-binding globulin, which might contribute to development of hyperlipidaemia in diabetic pregnancy." (PMID 34498500, 2021). "Additionally, a significant almost 60% drop in SHBG concentration was observed in women with hyperlipidemia." (PMID 34501389, 2021).
hypogonadotropic hypogonadism (9 papers, 2015 to 2025). Abnormal ovarian or testicular function due to insufficient hormonal stimulation from the hypothalamic-pituitary axis. "Researchers in 2004 analyzed concentration of testosterone, LH, and sex hormone-binding globulin (SHBG) and the incidence of hypogonadotropic hypogonadism in diabetic subjects." (PMID 35432804, 2021). "A major consequence is a reduction in effective testosterone, which arises due to both primary and hypogonadotrophic hypogonadism as well as altered SHBG levels." (PMID 28382300, 2017). "It seems that secondary hypogonadism occurs in obese and diabetic population, thus it is not surprising that in present study The present study showed the highest levels of serum testosterone and SHBG in the control group." (PMID 37208686, 2023). "For instance, dysfunction of the thyroid can result in decreased levels of the sex hormone-binding globulin (SHBG), which may in turn lead to secondary hypogonadism." (PMID 37893553, 2023). "Liver iron overload is associated with increased sex hormone-binding globulin (SHBG) and moderate hypogonadotropic hypogonadism in men with non-genetically dysmetabolic iron overload syndrome (DIOS)." (PMID 26646112, 2015).
ovarian carcinoma (9 papers, 2007 to 2025). A malignant neoplasm originating from the surface ovarian epithelium. "There are literature data on the association of the ZBTB10 gene with SHBG- and sex hormone-dependent tumors such as breast and ovarian cancers." (PMID 41373783, 2025). "The SHBG variants and their potential molecular and biological functions in human ovarian carcinoma are currently under investigation in our laboratory." (PMID 24386165, 2013). "Our results demonstrate that ovarian cancer cells produce SHBG and higher SHBG expression in ovarian carcinoma is associated with unfavorable clinicopathological features." (PMID 24386165, 2013). "None of the SNPs evaluated was significantly associated with ovarian cancer risk, including the putative functional SNPs SHBG D356N (rs6259) and -67G>A 5'UTR (rs1799941)." (PMID 17411440, 2007). "We performed a detailed assessment of common genetic variation in SHBG and evaluated the possibility of an association with ovarian cancer risk in the Polish Ovarian Cancer Study." (PMID 17411440, 2007). "Further, the observed allele frequency for the SHBG D356N was similar to previously published studies among Caucasians, and the distribution of ovarian cancer risk factors in cases and controls was consistent with known or suspected risk factors for ovarian cancer." (PMID 17411440, 2007). "SHBG expression is present in ovarian cancer (OC) and is found to unfavorably impact the pathological features of the cancer." (PMID 40427034, 2025). "In summary, we have found that SHBG is expressed in ovarian cancer cells, verified both in cell lines and clinical samples, and its expression is associated with unfavorable clinicopathological features." (PMID 24386165, 2013). "In our present study, we examined and found the variable SHBG expression in four ovarian cancer cell lines (OV-90, OVCAR-3, SKOV-3 and ES-2) by immunocytochemistry and Western blotting." (PMID 24386165, 2013). "Statistical analyses of histological subtype, histological grade and FIGO stage confirmed increased SHBG expression in more unfavorable ovarian carcinomas." (PMID 24386165, 2013). "We then extended our study to 248 ovarian carcinoma samples, which were collected at The Norwegian Radium Hospital, Oslo University Hospital with complete clinical information, and discovered that SHBG was variably expressed in these ovarian carcinomas." (PMID 24386165, 2013). "Cytoplasmic SHBG was detected by ICC in all of the four ovarian cancer cell lines ES-2, SKOV-3, OVCAR-3 and OV-90." (PMID 24386165, 2013). "Our present report is, to our best knowledge, the first study to systematically assess the localization and clinicopathological relations of the locally expressed SHBG in human ovarian carcinomas." (PMID 24386165, 2013). "Quantitative analysis of the blots revealed that the SHBG expressions in the four ovarian cancer cell lines agreed with the ICC finding: high in OV-90 and OVCAR-3, moderate in SKOV-3 and low in ES-2." (PMID 24386165, 2013). "Immunoreactive SHBG was variably detected in the ovarian carcinoma cells in all the ovarian primary tumor samples." (PMID 24386165, 2013). "We detected SHBG expression in all the four human ovarian cancer cell lines both by ICC and Western blotting, confirming the intracellular expression of SHBG in different histological subtype-derived cell lines." (PMID 24386165, 2013). "As a result, plasma SHBG is assumed to play a role in ovarian carcinoma clinical behaviors." (PMID 24386165, 2013). "Our finding that the ES-2 cell line was weakly positive for SHBG may imply a potential clinical role of SHBG in ovarian carcinoma although functional SHBG studies in consideration of this are warranted." (PMID 24386165, 2013). "This demonstrated that the local produced SHBG in ovarian cancer cells might probably influence the proliferative activity, invasiveness and distant metastasis of human ovarian carcinoma cells." (PMID 24386165, 2013).
ovarian carcinoma (continued). "The local expression of SHBG in human ovarian carcinoma cells and its clinicopathological correlations are currently unknown." (PMID 24386165, 2013). "Additional characterization of SHBG variants may help to further understand the molecular and biological roles of SHBG in ovarian carcinoma." (PMID 24386165, 2013). "We evaluated whether common genetic variation in SHBG and its 3' neighbor ATP1B2, in linkage disequilibrium, is associated with the risk of epithelial ovarian cancer." (PMID 17411440, 2007). "In our present study, we have investigated the expression of SHBG in four ovarian cancer cell lines by immunocytochemistry (ICC) and Western blotting, verifying variable SHBG expression in these cell lines." (PMID 24386165, 2013). "This detailed evaluation of common genetic variation in SHBG including its neighboring gene ATP1B2, does not support a substantial association between common variants and ovarian cancer risk." (PMID 17411440, 2007). "Given the lack of data from previous studies of ovarian cancer on the common variation in SHBG, further studies are needed to clarify potential relationships." (PMID 17411440, 2007). "The sex hormone-binding globulin (SHBG) is a carrier protein that modulates the bio-availability of serum sex steroid hormones, which may be involved in ovarian cancer." (PMID 17411440, 2007). "However, SHBG expression status and its clinicopathological significance in ovarian cancer cells are not reported yet." (PMID 24386165, 2013).
sexual dysfunction (9 papers, 2017 to 2025). Disturbances in sexual desire and the psychophysiologic changes that characterize the sexual response cycle and cause marked distress and interpersonal difficulty. "In males, sexual dysfunction was mainly caused by a hormonal imbalance that involved an increase in follicle-stimulating hormone, estrogen, and sex hormone-binding globulin and a decrease in dehydroepiandrosterone and the free androgen index." (PMID 38283448, 2023). "Additionally, sexual dysfunction in male epilepsy patients may be associated with increased follicle-stimulating hormone/sex hormone-binding globulin/prolactin levels as well as decreased GnRH and dehydroepiandrosterone sulfate levels, which can result in hypogonadism." (PMID 38283448, 2023). "In order to confirm the reliability of SHBG <33.4 nmol/L as a marker of metabolic impairment and increased NAFLD risk, a second larger independent cohort of women with sexual dysfunction was analyzed." (PMID 33854482, 2021). "Testosterone is an androgenic steroid hormone and binds to sex hormone-binding globulin and albumin, and low level of testosterone can result in sexual dysfunction." (PMID 28854246, 2017). "Therefore, we suggest to evaluate LH, SHBG, TT and cFT and sexual function during AMT, and start ART in the hypogonadal ACC patients with sexual dysfunction." (PMID 38269251, 2023). "Hence, we suggest a periodic LH, SHBG, TT and cFT monitoring during AMT, as well as an assessment of sexual function, to identify those patients with sexual dysfunction who might benefit from ART to, at least partially, improve their quality of life." (PMID 38269251, 2023). "Another study in 2006 focusing on premenopausal women with sexual dysfunction reported that SHBG levels were up to four times higher in OCP users than in those who had never used them and that SHBG levels remained elevated even after discontinuation." (PMID 40135042, 2025).
steatosis (9 papers, 2017 to 2025). Increased lipid within the cytoplasm of cells. "Low SHBG levels have been linked to higher liver fat, consistent with data showing SHBG overexpression reduces steatosis." (PMID 41153782, 2025). "A longitudinal cohort study that investigated the association between NAFLD and circulating SHBG levels showed an inverse association between SHBG levels and the severity of steatosis and portal inflammation." (PMID 39858445, 2025). "Circulating SHBG levels in patients with grade 2 steatosis tended to be higher than those in patients with grade 0 or grade 1 steatosis." (PMID 30487676, 2018). "The liver SHBG mRNA expression and serum SHBG level of Grade 1 steatosis was respectively 2.78- and 1.43-fold lower than that in tissues of Grade 0 (p < 0.05)." (PMID 30455723, 2018). "In addition, it is interesting to note that our patients with PCOS and steatosis showed lower SHBG levels and this finding is in agreement with the well-known data on the relationship between the liver production of SHBG and metabolic parameters." (PMID 29161258, 2017).
anovulation (8 papers, 2012 to 2025). The absence of ovulation. "Together, these results indicate that SHBG may contribute to reduced female infertility associated with anovulation." (PMID 38848344, 2024). "We conclude that current diagnostic tools, particularly the FAI and SHBG, demonstrate limited specificity in distinguishing PCOS from other causes of anovulation in adolescents." (PMID 40861046, 2025). "Interestingly, higher SHBG concentration in women provides a protective effect on female infertility, specifically in the case of anovulation." (PMID 40427034, 2025). "The IVW analysis demonstrated a negative causal link between SHBG and female infertility associated with anovulation (OR = 0.749, 95% CI0.645–0.871, P = 1.67×10−4)." (PMID 38848344, 2024).
atherosclerosis (8 papers, 2016 to 2025). A disease characterized by the build-up of fatty material and calcium deposition in the arterial wall resulting in partial or complete occlusion of the arterial lumen. "The SHBG promoter (TAAAA)n polymorphism is linked with early markers of atherosclerosis (impaired endothelium-dependent vasodilatation, increased carotid artery intima media thickness)." (PMID 40427034, 2025). "What is more, longer alleles of the promoter of SHBG ((TAAAA)n polymorphism) result in a higher risk of early atherosclerosis in healthy women." (PMID 40427034, 2025). "Low levels of SHBG have also been linked with indices for atherosclerosis such as coronary artery calcification or carotid artery intima-media thickness in women." (PMID 29213285, 2017). "For these reasons, our study showed that lower levels of SHBG constitute a risk factor for subclinical atherosclerosis, especially in obese women." (PMID 29213285, 2017). "Similar to our study, various studies have determined that low levels of serum SHBG constitute a risk factor for atherosclerosis and CVD in women." (PMID 29213285, 2017). "Only a few studies have investigated the association between SHBG levels and atherosclerosis in women." (PMID 29213285, 2017). "Based upon a previous review, insulin may mediate the association between SHBG production and atherosclerosis." (PMID 29213285, 2017). "Contrary to the findings in men, several studies have shown a significant relationship between SHBG levels and subclinical atherosclerosis in women." (PMID 29213285, 2017). "In men, although high levels of SHBG were associated with favorable BP and lipid profiles independent of testosterone, SHBG levels were not related to atherosclerosis." (PMID 29213285, 2017). "An important role in the pathogenesis of atherosclerosis is played by the genes ALB, SHBG, APOC, APOC3, APOC4, and SAA4, of which APOC3 and APOC4 make a major contribution to the occurrence of atherosclerosis and also to insulin resistance and type 2 diabetes." (PMID 40361926, 2025). "SHBG in T2/C1, T3/C1, T3/T2 (SCAD group/control group, AMI group/control group, AMI group/SCAD group) showed a trend of low expression and further confirmed that SHBG was negatively correlated with the atherosclerosis type." (PMID 34746269, 2021).
cognitive decline (8 papers, 2015 to 2024). "Fourth, one study found that increased serum-free estradiol was associated with reduced risk of cognitive decline, while higher SHBG (which binds and decreases free estradiol) increased risk." (PMID 37996855, 2023). "Although further research is necessary, therapeutic control of SHBG would allow endogenous estrogens and androgens to remain bioactive and potentially reduce the risk of cognitive decline." (PMID 25859241, 2015). "However, also previous studies reported that increased SHBG concentrations represent a risk for cognitive decline and were associated with low verbal memory scores in the elderly." (PMID 28498873, 2017). "Other SNP-trait pairings are: rs78049001, cognitive decline; rs2976530, hip bone mineral density; rs75986475, physical activity; rs78730126, sex hormone binding globulin measurement." (PMID 37345113, 2023). "SHBG levels and its inverse correlation with cognitive decline are important to consider for determining the efficacy of E2 and testosterone treatment." (PMID 25859241, 2015). "Consistently, we recently reported that higher levels of plasma SHBG contributed to accelerated Alzheimer’s pathology, declined brain metabolism, and atrophy of the hippocampus, which were known to be involved in the pathophysiology of cognitive decline." (PMID 33104518, 2020).
sarcopenia (8 papers, 2020 to 2024). Progressive decline in muscle mass due to aging which results in decreased functional capacity of muscles. "Some studies have suggested that elevated serum SHBG levels, alongside reduced total testosterone levels, are associated with increased mortality rates, malnutrition, sarcopenia, and frailty in males with T2DM." (PMID 39020340, 2024). "Additionally, high sex hormone-binding globulin (SHBG) levels have been associated with sarcopenia in both older men and women and was found to decrease in response to EONS intervention." (PMID 35334853, 2022). "Free testosterone, estradiol, and SHBG levels were shown to be substantially correlated with the parameter of sarcopenia (p < 0.0001), estradiol (p < 0.0001), and (p = 0.0002, respectively)." (PMID 36730272, 2023). "There are few studies relating sex hormone binding globulin (SHBG) with sarcopenia and their metabolic effects." (PMID 36362238, 2022). "Recently, the United Kingdom Biobank study demonstrated that high levels of SHBG are a potential biomarker of sarcopenia." (PMID 35370776, 2022). "Consequently, reduced bioavailable testosterone due to elevated SHBG levels might contribute to malnutrition, sarcopenia, and frailty." (PMID 39020340, 2024). "In individuals with ascites, sarcopenia, and Child-Pugh Class C sex steroid circumstances such as decreased free testosterone and elevated estradiol and SHBG may have an impact on the consistent outcomes between these three variables for lower sexual enjoyment." (PMID 36730272, 2023). "The concentration of other endocrine hormones, (Dehydroepiandrosterone, DHEAS; Sex-Hormone Binding Globulin, SHBG; and Insulin-like Growth Factor-1, IGF-1) are also associated with skeletal muscle and may be involved in the aetiology of sarcopenia since circulating concentrations change with age." (PMID 32443563, 2020). "On the contrary, SHBG, total T and E2/T ratio, years of HIV, and sarcopenia lost the statistical significance." (PMID 38643322, 2024). "The group with positive ascites, sarcopenia, and CPC-class C tended to have low free testosterone and high estrogen levels as well as SHBG in this sub-group analysis." (PMID 36730272, 2023). "First, total T (p = 0.002), E2/T ratio (p = 0.017), and cFT (p = 0.002) were significantly lower in MLWH with sarcopenia than those without; conversely, SHBG was higher in sarcopenic MLWH (p = 0.006)." (PMID 38643322, 2024).
thyroid (8 papers, 2018 to 2025). "Nevertheless, we see value in determining SHBG in men with thyroid diseases or with a past/family medical history of thyroid nodules." (PMID 40427034, 2025). "It is thought that thyroid hormones can regulate the transcription of sex hormone-binding globulin (SHBG), which has different binding affinities with testosterone and estradiol, thereby altering sex hormone levels." (PMID 37501165, 2023). "In women diagnosed with a thyroid disorder, we noticed significantly higher levels of MMP (p = 0.037) and SHBG (p = 0.042) during early pregnancy." (PMID 35327785, 2022).